XIST (X inactive specific transcript)
Diseases named in the same sentence as XIST in open-access papers (continued):
Sharing a sentence is not in itself a finding about the gene and the disease.
chordoma (1 paper, 2022). Chordomas are rare malignant tumors arising from embryonic remnants of the notochord in axial skeleton. "To investigate the biological role of XIST in chordoma cells, we performed loss-of-function experiments by transfection of shRNA in U-CH1 and JHC7 cells." (PMID 35899235, 2022). "Overexpression of ARF6 could abate the suppressive influence of XIST deficiency on chordoma cell growth, metastasis, and glycolysis." (PMID 35899235, 2022). "XIST knockdown inhibited chordoma progression via regulating the miR-320d/ARF6 axis, providing a novel insight into chordoma pathogenesis." (PMID 35899235, 2022). "In conclusion, our results proved that XIST knockdown suppressed chordoma cell growth, metastasis, and glycolysis as well as inhibited tumor growth in vivo by regulating the miR-320d/ARF6 axis." (PMID 35899235, 2022). "In this work, we demonstrated that XIST was highly expressed in chordoma, and its silencing limited chordoma cell proliferation, metastasis, and glycolysis via regulating the miR-320d/ARF6 axis." (PMID 35899235, 2022). "IHC analysis showed that XIST interference suppressed Ki67 (a proliferation marker) and cytokeratin (a chordoma marker) expression in tumor tissues." (PMID 35899235, 2022). "Overall, these results suggested that ARF6 overexpression abated inhibitory effects of XIST downregulation on chordoma cell proliferation, metastasis, and glycolysis." (PMID 35899235, 2022). "In chordoma, XIST expression is closely correlated with the poor prognosis of the patient, and XIST promoted chordoma cell proliferation and inhibited apoptosis." (PMID 35899235, 2022). "MTT assay, EdU assay, and colony formation assay showed that XIST silencing repressed cell viability, DNA synthesis, and colony formation ability in U-CH1 and JH7C cells, indicating that XIST knockdown inhibited chordoma cell proliferation." (PMID 35899235, 2022). "Next, the localization of XIST was determined in chordoma cells (U-CH1 and JHC7)." (PMID 35899235, 2022). "We found that the XIST level was enhanced in chordoma tissues in contrast to normal tissues." (PMID 35899235, 2022). "In our work, we explored XIST expression in chordoma samples." (PMID 35899235, 2022). "In our research, XIST upregulation was also observed in chordoma tissues." (PMID 35899235, 2022). "•XIST positively upregulated ARF6 expression via sponging miR-320d in chordoma cells." (PMID 35899235, 2022). "XIST silencing repressed chordoma cell proliferation, migration, invasion, and glycolysis." (PMID 35899235, 2022). "To determine whether XIST regulated chordoma cell behaviors by targeting ARF6, we performed rescue experiments in U-CH1 and JHC7 cells." (PMID 35899235, 2022). "•XIST knockdown inhibited chordoma progression by downregulating ARF6." (PMID 35899235, 2022). "Moreover, chordoma patients with high XIST expression had a poor overall survival than patients with low XIST expression." (PMID 35899235, 2022). "XIST knockdown suppressed chordoma cell proliferation, migration, invasion, and glycolysis." (PMID 35899235, 2022). "Furthermore, overexpression of ARF6 reversed the inhibitory effects of XIST knockdown on chordoma cell proliferation, migration, invasion, and glycolysis." (PMID 35899235, 2022). "Collectively, these in vivo data indicated that XIST downregulation could inhibit the tumorigenicity of chordoma." (PMID 35899235, 2022). "All these data indicated that XIST knockdown inhibited the progression of chordoma cells." (PMID 35899235, 2022). "Next, we explored whether XIST played a critical role in glycolysis in chordoma cells." (PMID 35899235, 2022). "Importantly, XIST downregulation inhibited the tumorigenesis of chordoma in vivo." (PMID 35899235, 2022). "However, more roles and regulatory mechanisms of XIST in chordoma are still largely unknown." (PMID 35899235, 2022).
chordoma (continued). "In addition, the relationships among XIST, miR-320d, and ARF6 in chordoma cells were also investigated using bioinformatic databases and a series of experiments." (PMID 35899235, 2022). "A negative correlation between miR-320d and XIST expression was observed in chordoma tissues." (PMID 35899235, 2022).
chronic hepatitis C infection (1 paper, 2025). "In addition, despite the limited number of patients with chronic hepatitis C infection, XIST expression was significantly associated with hepatitis C virus (HCV) positivity in the entire study group (4/5, p=0.029)." (PMID 39397388, 2025).
colorectal tumour (1 paper, 2022). "XIST was the highest expressed transcript when miR‐210 was inhibited in both cells and tumours, thus high XIST expression was correlated with decreased colorectal tumour growth." (PMID 36116139, 2022).
congenital heart disease (1 paper, 2024). A heart disease that is present at birth. "Similarly, XIST has also been recognized to be associated with various congenital heart disease subtypes." (PMID 39202774, 2024). "XIST has been widely reported to participate in congenital heart disease through various lncRNAs-miRNAs regulation." (PMID 39202774, 2024).
cystic fibrosis (1 paper, 2017). Autosomal recessive disorder caused by pathogenic variants in the CFTR gene (cystic fibrosis transmembrane conductance regulator), which encodes a chloride and bicarbonate channel expressed in epithelial cells, and follow the diagnosis criteria. "Moreover, XIST has been reported to highly express in cystic fibrosis bronchial epithelium, suggesting the potential relation between XIST and fibrosis." (PMID 29029436, 2017).
diffuse astrocytoma (1 paper, 2018). A low-grade (WHO grade II) astrocytic neoplasm. "The high expression of XIST has been shared by most of the diffuse astrocytoma, validating their efficacy and accuracy of such rules." (PMID 30322114, 2018). "Apart from XIST, the two homologues, namely, RPL7 and RPL8, have also been predicted to have quantitative patterns in diffuse astrocytoma." (PMID 30322114, 2018).
epilepsy (1 paper, 2021). A brain disorder characterized by episodes of abnormally increased neuronal discharge resulting in transient episodes of sensory or motor neurological dysfunction, or psychic dysfunction. "The RT-qPCR results revealed that XIST expression in epilepsy rat models was markedly higher than that observed in normal rats." (PMID 33776905, 2021). "In this study, XIST expression was found to be significantly up-regulated in the rat epilepsy model." (PMID 33776905, 2021). "XIST expression and NFAT5 protein level was increased, whereas miR-29c-3p expression was decreased in the epilepsy rat model and LPS-treated CTX-TNA2 cells." (PMID 33776905, 2021). "XIST and NFAT5 expression was increased while miR-29c-3p expression was decreased in epilepsy rat models and LPS-stimulated CTX-TNA2 cells." (PMID 33776905, 2021). "To explore the role of XIST in epilepsy, we assessed the XIST expression in epilepsy rat models and CTX-TNA2 cells treated with or without LPS." (PMID 33776905, 2021). "miR-29c-3p expression was found to be significantly reduced in the rat epilepsy model, which had negative relationship with XIST expression." (PMID 33776905, 2021). "Furthermore, XIST, NFAT5, and miR-29c-3p effect on epilepsy rat model were not elucidate." (PMID 33776905, 2021).
head and neck squamous cell carcinoma (1 paper, 2021). A squamous cell carcinoma that arises from any of the following anatomic sites: lip and oral cavity, nasal cavity, paranasal sinuses, pharynx, larynx, and salivary glands. "The Cancer Genome Atlas (TCGA) database showed that higher XIST expression is associated with a poorer prognosis for patients with head and neck squamous cell carcinoma (HNSCC)." (PMID 34295808, 2021).
HIV-1 infection (1 paper, 2017). The type species of lentivirus and the etiologic agent of acquired immunodeficiency syndrome (AIDS). "XIST expression was initially upregulated by glial humanization and downregulated by HIV-1 infection." (PMID 29084769, 2017).
hypoplastic left heart syndrome (1 paper, 2024). Hypoplastic left heart syndrome (HLHS) refers to the abnormal development of the left-sided cardiac structures, resulting in obstruction to blood flow from the left ventricular outflow tract. "The specific role of XIST (X Inactive Specific Transcript) in HF-hypoplastic left heart syndrome has been reported to be associated with the specific inactivation of the ring X chromosome." (PMID 39202774, 2024).
infertile (1 paper, 2019). "Given the correlation with spermatogenesis efficiency, assessment of XIST demethylation levels in semen samples from infertile patients will be of interest as a non-invasive way for better grouping of these patients and deciding on the best treatment option." (PMID 31533343, 2019).
Insulin resistance (1 paper, 2022). Increased resistance towards insulin, that is, diminished effectiveness of insulin in reducing blood glucose levels. "The role of XIST in insulin resistance and T2DM has also been reported." (PMID 36092798, 2022).
intestinal cancer (1 paper, 2023). "This is relevant as to whether XIST function appears crucial, notably in specific blood and intestinal cancers." (PMID 37759468, 2023).
juvenile idiopathic arthritis (1 paper, 2024). Juvenile idiopathic arthritis (JIA) is the term used to describe a group of inflammatory articular disorders of unknown cause that begin before the age of 16 and last over 6 weeks. "Moreover, the analysis of GEO drug discovery showed that methotrexate could significantly decrease the expression of XIST in patients with juvenile idiopathic arthritis with an FDR < 0.05." (PMID 38486041, 2024).
Kawasaki disease (1 paper, 2023). A rare inflammatory disease characterized by an acute febrile, systemic, self-limiting, medium-vessel vasculitis primarily affecting children. "In this study, the TOP4 lncRNAs common to most miRNAs were exhibited, the studies have found that The NEAT1/NORAD/XIST has-miR-204 axis regulates the development of Kawasaki disease (KD)." (PMID 37483435, 2023).
kidney neoplasm (1 paper, 2022). A benign or malignant neoplasm affecting the kidney. "For instance, prognostic roles of XIST between BRCA and kidney neoplasms were opposite, which might attribute to different types of cells, sources of germ layers and effects of hormone." (PMID 36212008, 2022).
laryngeal squamous cell carcinoma (1 paper, 2023). A squamous cell carcinoma that arises from the larynx. "Previous studies have shown that lncRNA XIST promotes the development of laryngeal squamous cell carcinoma (LSCC) through stimulating miR-144 to regulate the expression of IRS1; interference with its expression can inhibit the proliferation, migration, and invasion of LSCC cells." (PMID 37504269, 2023).
Lesch-Nyhan syndrome (1 paper, 2019). Lesch-Nyhan syndrome (LNS) is the most severe form of hypoxanthine-guanine phosphoribosyltransferase (HPRT) deficiency, a hereditary disorder of purine metabolism, and is associated with uric acid overproduction (UAO), neurological troubles, and behavioral problems. "Expression of one XIST SNP in selected human female carrier Lesch-Nyhan syndrome fibroblasts with coalescent X-chromosomes supports Xist localization changes occurring during coalescence as opposed to XIST reactivation on the Xa." (PMID 31142749, 2019).
medulloblastoma (1 paper, 2021). A malignant, invasive embryonal neoplasm arising from the cerebellum. "To ascertain the role of these deregulated lncRNAs in the radiosensitivity of medulloblastoma cells, we knocked down RBM5-AS1, DANCR, and MALAT1 and overexpressed XIST in DAOY cells." (PMID 34225779, 2021).
mental retardation (1 paper, 2022). "The risk of mental retardation (usually very rare in TS) is higher in patients with a marker chromosome or a ring X chromosome, which does not contain the XIST gene." (PMID 35821070, 2022).
metastatic melanoma (1 paper, 2012). A melanoma that has spread from its primary site to another anatomic site. "Additionally, we investigated by RT-PCR the expression of XIST in two female patient-derived metastatic melanoma cell lines with high degree of aggressiveness (Mel-11 and Mel-33)." (PMID 22984562, 2012).
oligodendroglioma (1 paper, 2023). A well-differentiated (WHO grade II), diffusely infiltrating neuroglial tumor, typically located in the cerebral hemispheres. "Finally, we conducted a permutation test using the lncRNA XIST and its target NGS genes in the oligodendroglioma dataset to check whether NGS gene regulation by lncRNAs could occur by chance." (PMID 37693314, 2023).
Peri-Implantitis (1 paper, 2024). An inflammatory process with loss of supporting bone in the tissues surrounding functioning DENTAL IMPLANTS. "In the context of existing research, this study determined the expression of salivary XIST in patients with peri-implantitis, and subsequently explored the diagnostic ability of XIST to identify patients with peri-implantitis and patients with healthy peri-implant tissues." (PMID 39105315, 2024). "Furthermore, XIST was able to distinguish peri-implantitis patients from controls, and logistic regression analysis elucidated the potential of XIST as a risk factor for peri-implantitis." (PMID 39105315, 2024). "Meanwhile, XIST may be a diagnostic marker for peri-implantitis with positive clinical potential in the prevention and treatment of patients." (PMID 39105315, 2024). "By measuring and analysing the content of XIST in saliva samples of patients, we revealed that prominently expressed XIST has a high diagnostic value in early peri-implantitis, providing a new reference for the treatment of patients and the study of related molecular mechanisms." (PMID 39105315, 2024). "Salivary XIST levels were obviously higher in patients with peri-implantitis than in the healthy control group, and the AUC value for identifying patients was 0.8742 with a sensitivity and specificity of 83.5% and 81.4%." (PMID 39105315, 2024). "XIST was overexpressed in the saliva of patients with peri-implantitis and correlated with the severity of the disease." (PMID 39105315, 2024). "RT-qPCR assay revealed that the expression of XIST in patients with peri-implantitis (n=97) was elevated compared to the healthy control group (n=80)." (PMID 39105315, 2024). "XIST expression in saliva of patients with peri-implantitis was detected by qRT-PCR." (PMID 39105315, 2024). "In this study, XIST was verified to be upregulated in patients with peri-implantitis." (PMID 39105315, 2024). "Based on this, XIST may be involved in the process of peri-implantitis through sponge miR-150-5p; the molecular mechanism and the inflammatory factors involved are targets of our future research." (PMID 39105315, 2024). "Moreover, the possible regulatory mechanism of XIST in peri-implantitis was revealed based on the competitive binding relationship between lncRNA and microRNA (miRNA)." (PMID 39105315, 2024). "Patients in the peri-implantitis group had higher levels of plaque index (PLI), sulcus bleeding index (SBI) and probing depth (PD) than those in the healthy control group, and the expression of XIST was positively correlated with PLI, SBI, and PD levels." (PMID 39105315, 2024).
pertussis (1 paper, 2023). A contagious bacterial respiratory infection caused by Bordetella pertussis. "The ceRNA network including miRNA-lncRNA-mRNA showed that lncRNA XIST and NEAT1 have the most important role among other lncRNAs in the network by affecting five common miRNAs related to human genes involved in staphylococcus aureus infection and pertussis." (PMID 37169818, 2023).
primary immunodeficiency (1 paper, 2025). "As expected, multiple cell pairs showed XIST-correlated genes enriched in immune-related pathways, including antigen processing and presentation and primary immunodeficiency (Sup." (PMID 40999523, 2025).
schizophrenia (1 paper, 2024). A major psychotic disorder characterized by abnormalities in the perception or expression of reality. "Additionally, enhancers from female-specific TRDs were found to regulate two genes known to escape XCI, (XIST and JPX), underlying the importance of TRDs in deciphering sex differences in schizophrenia." (PMID 38645177, 2024).
Sertoli Cell-Only Syndrome (1 paper, 2019). A type of male infertility in which no germ cells are visible in any of the biopsied SEMINIFEROUS TUBULES (type I) or in which germ cells are present in a minority of tubules (type II). "XIST is not expressed in the testis with only premeiotic cells or in the case of Sertoli-cell only syndrome, but starts to be expressed around the time germ cells enter meiosis." (PMID 31533343, 2019).
spinal cord injury (1 paper, 2022). Penetrating and non-penetrating injuries to the spinal cord resulting from traumatic external forces (e.g., WOUNDS, GUNSHOT; WHIPLASH INJURIES; etc.). "The suppression of XIST after spinal cord injury (SCI) enhances the function of the XIST/miR-27a/Smurf1 pathway and causes the inhibition of miR-494." (PMID 36402997, 2022).
Stroke (1 paper, 2024). Sudden impairment of blood flow to a part of the brain due to occlusion or rupture of an artery to the brain. "Previous investigations have identified key stroke-sensitive lncRNAs involved in epigenetic regulation, such as FosDT, HOTAIR, H19, GAS5, MEG3, XIST, and TUG1." (PMID 40789569, 2024).
teratoma (1 paper, 2010). A non-seminomatous germ cell tumor characterized by the presence of various tissues which correspond to the different germinal layers (endoderm, mesoderm, and ectoderm). "We then asked whether XIST expression can be induced in hESCs that do not express XIST upon teratoma differentiation." (PMID 20593031, 2010).
testicular tumor (1 paper, 2022). "LncRNAs that alter testicular tumor pathogenesis such as XIST, H19, SPRY4-IT, NLC1-1C, and HOTTIP, but most of them have not been evaluated in clinical studies, except for XIST." (PMID 35454102, 2022).
Tetralogy of Fallot (1 paper, 2024). A congenital cardiac malformation comprising pulmonary stenosis, overriding aorta, ventricular septum defect, and right ventricular hypertrophy. "Although no direct reports confirmed the association between XIST (X Inactive Specific Transcript, 300936) and Tetralogy of Fallot, abnormal XIST (X Inactive Specific Transcript) expression has been widely observed in different CHD subtypes." (PMID 39202774, 2024).
thyroid (1 paper, 2021). "Various cancers such as thyroid and osteoscaroma have also shown XIST to act as an oncogene, which coincides with our findings in HNC." (PMID 34733782, 2021).
tongue cancer (1 paper, 2021). A malignant neoplasm affecting the tongue. "Moreover, our results showed increased expression of XIST in human tongue cancer." (PMID 34295808, 2021).
tongue squamous cell carcinoma (1 paper, 2021). A squamous cell carcinoma that arises from the tongue. "The data indicated that CAL27 and SCC9 tongue squamous cell carcinoma (TSCC) cells had reduced expression of X-inactive specific transcript (XIST) after CuB treatment." (PMID 34295808, 2021).
type 2 diabetes (1 paper, 2018). "Compared to control subjects, expression levels of lncRNAs in PBMCs from type 2 diabetes patients showed significantly (p < 0.05) increased levels of HOTAIR, MEG3, LET, MALAT1, MIAT, CDKN2BAS1/ANRIL, XIST, PANDA, GAS5, Linc-p21, ENST00000550337.1, PLUTO, and NBR2." (PMID 30139387, 2018). "Compared to control subjects, expression profiling of lncRNAs in PBMCs from type 2 diabetes patients showed significantly (p < 0.05) increased levels of HOTAIR, MEG3, LET, MALAT1, MIAT, CDKN2BAS1/ANRIL, XIST, PANDA, GAS5, Linc-p21, ENST00000550337.1, PLUTO, and NBR2." (PMID 30139387, 2018).